CXCR1 (C-X-C motif chemokine receptor 1)
Diseases named in the same sentence as CXCR1 in open-access papers (continued):
Sharing a sentence is not in itself a finding about the gene and the disease.
tumor (continued). "Mice were then treated with CAR-T cells overexpressing CXCR1 or CXCR2, which led to significant tumor regression and appeared to demonstrate a synergy between radiotherapy and chemokine-targeted CAR-T treatment." (PMID 38339310, 2024). "In vitro experiments have shown that a dual CXCR1/CXCR2 inhibitor, such as SCH-479833 and SCH-527123, has an anti-tumor effect on malignant melanoma." (PMID 38673949, 2024). "Focusing on PCa, therapeutic inhibition of IL-8 or its receptors CXCR1 and CXCR2 demonstrated reduced tumour growth and increased treatment sensitivity in resistant tumours." (PMID 39199570, 2024). "Both MDA-PCa-2b-CXCR1 (5.075 ± 1.284) and MDA-PCa-2b-CXCR2 (5.175 ± 1.162) showed a significant reduction in tumor infiltrating CD45+ cells relative to MDA-PCa-2b-Vec (8.150 ± 1.471)." (PMID 39766038, 2024). "CXCR 1 and CXCR2 CAR-T cells maintain continuous tumor decline and immune memory in various tumor models such as glioblastoma, ovarian cancer, and pancreatic cancer." (PMID 38664743, 2024). "CXCR1 expression in both MDA-PCa-2b and LNCaP cells inhibited tumor growth; whereas, CXCR2 expression, as previously reported, promoted tumor growth." (PMID 39766038, 2024). "TAMs and TANs can be recruited into the tumor microenvironment by chemokines produced by cancer cells, such as the chemokines signaling axis CXCL1, CXCL2, CXCL5, CXCL8–CXCR2, and CXCR1." (PMID 39769501, 2024). "Three target receptors (CXCR1, DcR3, and OPG) were selected for their significant roles in cancer pathogenesis and tumor cell proliferation." (PMID 38388460, 2024). "To further investigate the effect of CXCR1 expression in tumor growth, we carried out RNA sequencing analysis of MDA-PCa-2b-Vec, MDA-PCa-2b-CXCR1, and MDA-PCa-2b-CXCR2 cells." (PMID 39766038, 2024). "In these patients, CXCR1 modulated the tumor microenvironment as well as the PI3K/AKT and ERK pathways, which are shared by CXCR1 and EGFR-TKI." (PMID 39114657, 2024). "The axis of CXCL1/CXCR1, a receptor of CXCL1, activated the MAPK kinase pathway to tumor progression." (PMID 38393465, 2024). "ELR+CXCL produced by tumour cells bind to CXCR1/2 expressed by TAM, TAN, and MDSC and thus promote their activation and retention in the tumour." (PMID 38397987, 2024). "Understanding the complex interactions between IL-8, CXCR1, and CXCR2 within the TME is crucial for developing targeted therapeutic strategies for PCa and addressing tumour progression, dissemination, and treatment resistance." (PMID 39199570, 2024). "We observed increased expression of receptors such as CXCR2, CXCR1, and CSF3R in TAN that have been reported to be crucial for neutrophil recruitment to the tumor parenchyma." (PMID 38358826, 2024). "It was demonstrated that CXCR1 and CXCR2-modified CD70 CARs downregulated the expression of exhaustion markers on T cells and upregulated the migration of T cells in the tumor." (PMID 38201305, 2024). "Therefore, it could be that the immunosuppressive effect of CXCR1 expression in tumor growth is due to both the activation of pro-angiostatic chemokine receptors as well as the recruitment and activation of leukocytes into the tumor microenvironment." (PMID 39766038, 2024). "The interaction between IL-8 and its receptors CXCR1/2 can promote tumour cell survival through the EMT, which enhances the migratory ability of tumour cells." (PMID 39199570, 2024). "We also determined the effect of CXCR1 and CXCR2 overexpression in tumor growth in nude mice xenografts." (PMID 39766038, 2024). "Consistently, the tumor growth and metastatic potentials of ID8 Cxcr1/2 CRISPRi cells with GFP/Luc were remarkably reduced in the WT mice as well as the Yap1+/− and Yap1−/− mice without any apparent change in survival and body weight." (PMID 36624516, 2023). "CXCR1 and CX3CR1 expression levels were significantly correlated with tumor purity and the infiltrating levels of macrophages and NKT in LUAD." (PMID 37770496, 2023).
tumor (continued). "CXCL8 mainly functions through its interactions with CXCR1 and CXCR2, and CXCL8/CXCR1 contributes to the proliferation of tumor cells." (PMID 36647133, 2023). "These varying aspects between CXCR1 and CXCR2 lead to more questions about how they function in the tumor microenvironment, specifically pertaining to how they affect tumor cells." (PMID 36831112, 2023). "This is further enhanced by infiltration of CXCR1- or CXCR2-expressing MDSCs, which further promote tumor growth by inhibiting local anti-tumor immune responses mediated by CD8+ T-lymphocyte infiltration and cytotoxicity." (PMID 36725964, 2023). "Our study reported that CXCR1 and CX3CR1 expressions were significantly negatively correlated with tumor purity whereas significantly positively correlated with infiltrating levels of macrophage in LUAD, especially M2 macrophages." (PMID 37770496, 2023). "Instead, CCR6 alone was as efficient or even more efficient in directing T cells into the tumor as was dual transduction with CCR6 and CXCR1 or CCR6 and CX3CR1." (PMID 37301772, 2023). "CRC cells are able to regulate CXCL8 in an autocrine manner and increase the expression of CXCR1 and CXCR2, which contributes to tumor development through the invasion, dissemination and metastasis of cancer cells." (PMID 37509572, 2023). "CXCR1 and CXCR2 have comparable affinity to CXCL6 and CXCL8 (IL-8), and CXCR2 mediates tumor angiogenesis." (PMID 37626511, 2023). "A significant area of further exploration includes examining all the CXCR1 and CXCR2 downstream pathways elicited by each ligand in the tumor cells." (PMID 36831112, 2023). "The tumor microenvironment (TME) can secrete CXC chemokine ligands, attracting neutrophils, which possess high levels of chemokine receptors CXCR1 and CXCR2, to the site of the tumor, in a process called chemotaxis." (PMID 37261342, 2023). "Treating antibodies against the IL-8 receptor CXCR1 and repertaxin (CXCR1/CXCR2 inhibitor) targets BCSCs in xenograft models, thus reducing the EMT and tumor growth." (PMID 38090567, 2023). "Tumor-produced chemokines, acting through CXCR1 and CXCR2 chemokine receptors, can induce NETosis and aid immune evasion of cancers by physically coating tumor cells and preventing contact with CD8 and NK cells." (PMID 37143649, 2023). "Neutrophils have high expression of CXCR1 and CXCR2, both of which interact with their ligands secreted by tumor cells, stromal cells, endothelial and immune cells in the TME, thus promoting their recruitment to tumor sites." (PMID 36514901, 2022). "Chemokines (CXCL12, CXCL8, CXCL5) and chemokine receptors (CXCR1/2, CCR4, CCR8) are well-known to deeply participate in the tumor development and progression in various cancers, including LUAD." (PMID 36419650, 2022). "By binding to CXCR1 and CXCR2, CXCL7 can affect tumor proliferation, invasion, migration, and tumor angiogenesis in an autocrine and paracrine manner through multiple signaling pathways." (PMID 35837284, 2022). "Evidence suggests that tumor cells promote the release of NETs from neutrophils through stimulation, such as secretion of IL-8/CXCL8 and CXCR1/CXCR2 agonists, which provides an explanation for the link between NETs and cancer." (PMID 36341351, 2022). "This possibility is highly supported by the fact that joint inhibition of CXCR1/2, CCR2 and CCR5 led to complete inhibition of tumor cell invasion and of CCL2 and CCL5 production." (PMID 35205789, 2022). "ARID3B, CXCR1, GATS, Itga6, Shh, SLC27A5, STC2, and VEGF play an important role in cell proliferation and tumor progression or metastasis." (PMID 35875133, 2022). "Cytokines CXCL1, CXCL2, and CXCL8 in Cancer Cells interact with CXCR1 and CXCR2 in Neutrophils, chemotactic the activity of Neutrophils, and promote the generation of tumor immune microenvironment." (PMID 36401283, 2022).
tumor (continued). "Navarixin is a CXCR1/CXCR2 receptor antagonist that impairs neutrophils recruitment, and that was shown to repress tumor cells metastasis and angiogenesis in preclinical models." (PMID 36591453, 2022). "Of note, the transition to HLA-DR+ neutrophils was accompanied by a shift toward the identified TAN signature (elevated expression of CD83 and LOX-1 and lower expression of CD181 [CXCR1], CD62L [SELL], and CD16) in neutrophils derived from NSCLC tumor tissue." (PMID 36368318, 2022). "At 72 h, colon and tumour tissue were collected and examined for histopathological changes and RT-PCR for genes of interest; TLR4, MD-2, CD-14, MyD88, IL-6, IL-6R, CXCL2, CXCR1, and CXCR2." (PMID 35962138, 2022). "Cancer cells trigger NETosis by CXCR1 and CXCR2 activation; NETs protect tumor cells from contact with cytotoxic T cells and NK cells, promoting cancer cell dissemination and lung metastasis." (PMID 35574410, 2022). "In detail, genetic modification of CAR-Ts for the expression of IL-8 receptors (CXCR1 or CXCR2) and the utilization of the tumor-secreted IL-8 to usher the IL-8 receptor-modified CAR-Ts (IL-8R-CAR-Ts) to the tumor foci results in enhanced antitumor activity." (PMID 35634281, 2022). "Given the presence of CXCR1 and CXCR2 receptors on endothelial cells, cancer cells, and TANs, increased IL-8 secretion from tumor cells has a broader significance for the TME." (PMID 36419156, 2022). "Recent studies demonstrate that SX-682, an oral CXCR1/2 inhibitor, disrupts MDSC trafficking, and improves tumor control by anti-PD1 therapy in an oral cancer model, as previously shown in other tumor models." (PMID 35937775, 2022). "BATF3- and CXCR1-DCs secrete CD141, which primes CD8+ T cells for anti-tumor activity and generates CXCL10 to recruit specific CD8+ T cells." (PMID 35205408, 2022). "Chemokines CXCL1, CXCL2, and CXCL8 are highly expressed in Cancer Cells and act on CXCR1 and CXCR2, which are highly expressed in Neutrophil chemotactic the activity of Neutrophils and promote the generation of tumor immune microenvironment." (PMID 36401283, 2022). "CAR-NK cells express CXCR1 and are induced to migrate toward cancer cells by secreted CXCL8, exerting tumor- suppressive effects." (PMID 35269786, 2022). "Neutrophil-attracting chemokines, such as CXCL1, CXCL2, or CXCL8, are induced in hypoxic tumor tissue, through the activation of hypoxia-inducible factor 1 (HIF-1α or β), and support neutrophil migration to the tumor site via CXCR1 and CXCR2 receptors." (PMID 35158807, 2022). "Neutrophils express chemokine receptors CXCR1 and CXCR2 56, and tumor cells express the ligands of these receptors, thereby promoting the recruitment of tumor associated neutrophils." (PMID 36276645, 2022). "IL-8 is known for B-cell progression and Chemokine receptors CXCR1/2 and their ligand CXCL8 are essential for the activation and trafficking of inflammatory mediators as well as tumor progression and metastasis." (PMID 33802234, 2021). "IL-8 and its receptors CXCR1 and CXCR2 are overexpressed in HNSCC and involved in progression, metastasis, and aggressive tumor phenotype." (PMID 33925575, 2021). "The chemokine receptor, such as CXCR1, also enhanced the trafficking of CAR-NK cells to tumor lesion, subsequently augmenting the anti-tumor response." (PMID 34209505, 2021). "The migration of neutrophils to tumors is mainly mediated by CXC chemokine binding to CXCR1 and CXCR2, which can promote tumor growth, invasion, angiogenesis, and metastasis." (PMID 34604045, 2021). "In this experimental setting, the authors demonstrated that tumor-secreted CXCR1 and CXCR2 ligands, Interleukin 8 (IL-8 or CXCL-8), induce extrusion of NETs protecting tumor cells from CTL and the natural killer cell (NK) cytotoxicity." (PMID 34261496, 2021). "Tumor cells use chemokines to attract TANs to the tumor site, such as the potent neutrophil chemoattractant CXCL8, which entrains the CXCR1 and CXCR2 expression on neutrophils." (PMID 33936029, 2021).
tumor (continued). "Blocking CXCR1 and CXCR2 with small molecule inhibitor SX-682 significantly abrogated CXCR2+PMN-MDSC tumor accumulation and enhanced the efficacy of both the PD-axis immune checkpoint blockade and adoptive cell transfer of engineered T cells." (PMID 35011369, 2021). "Treatment with a small-molecule antagonist of CXCR1/2, the receptor of CXCL8, was demonstrated to promote tumor progression in animal models established with CT26 cancer cells." (PMID 34025668, 2021). "The CXCR1 and CXCR2 inhibitor Reparixin was also able to improve tumor cell apoptosis and decrease tumor volume in a gastric cancer model, when in combination with 5-fluorouracil." (PMID 34575965, 2021). "In their U87 glioma mouse model, CAR T cells with both CXCR1 and CXCR2 showed enhanced migration to the tumor and decreased tumor growth compared to the control groups." (PMID 34203660, 2021). "IL8, CXCL2, CXCR1 and CXCR2 are expressed by various GBM tumor cell lines as well as by tumor cells and endothelial cells in GBM patients." (PMID 34203660, 2021). "CXCR1/2-modified CAR-T cells enhance T-cell trafficking, persistence of T cells in the tumor, long-lasting immunologic memory, and therapy efficacy in aggressive solid tumors such as glioblastoma, ovarian, and pancreatic cancer." (PMID 35011369, 2021). "The results showed that TTCS was superior to NTSC in inducing the migration of tumor‐infiltrating neutrophils, and this effect was almost lost when these neutrophils were pre‐treated with CXCL6/CXCL8 and/or CXCR1 blocking antibodies." (PMID 34185422, 2021). "The different behaviors of reparixin or danirixin depend on the specific target, such as targeting CXCL8, CXCR1/CXCR2 or CXCR2, or depend on the specific target cells, such as tumor cells or different immune cell subpopulations." (PMID 34025668, 2021). "In human BC PDX, the use of a specific antibody against IL-8 receptor, CXCR-1, or an inhibitory molecule against to CXCR-1 and CXCR-2, repertaxin, favored the eradication of CSC pool, thus impeding tumor progression." (PMID 34354950, 2021). "These chemokines interact with the promiscuous chemokine receptor, CXCR2, expressed on neutrophils, as well as on many types of tumor cells, to initiate the influx of pro-tumoral neutrophils of the MDSC phenotype, while IL-8 interacts selectively with CXCR1." (PMID 32244751, 2020). "Inhibitors of CXCR1/2 also showed that these receptor/s controlled the expression of EMT markers and induced elevations in tumor cell invasion." (PMID 33585241, 2020). "The pronounced effect of targeting CXCR1 and CXCR2 signalling observed in our in vivo models is consistent with the multifactorial role of chemokines within the tumour microenvironment." (PMID 32743555, 2020). "The cellular endpoint effects induced by the IL-8 CXCR1/CXCR2 axis, in normal epithelial cells, tumor cells or other cells in the tumor microenvironment, promote cellular survival, proliferation, angiogenesis, and a stem cell phenotype." (PMID 32793466, 2020). "SX-682 is an orally available allosteric inhibitor of CXCR1 and CXCR2 that has shown promise in promoting tumor regression pre-clinically." (PMID 34458892, 2020). "CXCR1 and CXCR2 are kinds of G protein–coupled receptors, and activation of receptors can contribute to many actions including angiogenesis and tumour growth." (PMID 32588946, 2020). "The CXCR1 and CXCR2 inhibitor SX-682 has already proven to promote tumor clearance following adoptive cell transfer of tumor antigen specific T cells in mouse models of squamous cell carcinomas." (PMID 34458892, 2020). "Antagonists of CXC receptors, specifically dual antagonists of CXCR1 and CXCR2, have the potential to interfere with tumor-orchestrated recruitment of neutrophils/MDSCs into the TME." (PMID 32244751, 2020). "In head and neck and lung tumor-bearing mice, treatment with SX-682, a small inhibitor of both CXCR1 and CXCR2, resulted in abrogation of tumor infiltrating MDSCs." (PMID 33203092, 2020).
tumor (continued). "Our initial studies confirmed the increased expression of CXCL8 and its two receptors CXCR1 and CXCR2 in the tumour epithelium of human CaP." (PMID 32743555, 2020). "Inhibitors of CXCR1 and CXCR2 efficiently inhibit the growth of experimental HNSCC and RCC by decreasing tumor cell proliferation, angiogenesis and inflammation." (PMID 32775327, 2020). "We previously reported that the competitive CXCR1/2 inhibitor, SB225002, delays in vivo tumor growth and inflammation by antagonizing the signaling pathways induced by CXCL7." (PMID 31410218, 2019). "While both IL-8 receptors, CXCR1 and CXCR2, can regulate tumor cell proliferation and metastasis in a variety of cancers, signaling via CXCR2 appears to have a more pronounced effect." (PMID 31227783, 2019). "IL-8 displays its biological functions, through its binding to the heterotrimeric G protein-coupled receptors, CXCR1 and CXCR2, expressed by monocytes, as well as endothelial, tumor and stromal cells." (PMID 35582268, 2019). "Alyssa D. Gregory and A. Mc Garry Houghton suggest two different possible strategies: (a) targeting the “CXCL-8/CXCR-1/CXCR-2 axis,” thereby entirely exhausting TANs or (b) targeting specific PMN-derived substances able to induce tumor growing." (PMID 31799175, 2019). "Neutrophils and myeloid derived suppressor cells (MDSCs) are recruited to the tumor through ligands for CCR2, CCR3, CXCR1, CXCR2, and CXCR4." (PMID 30873179, 2019). "Neutrophils recruited to the tumor via CXCR2 can aid tumor progression and inhibition of CXCR1 and CXCR2 has shown promise in mouse models and human cancers." (PMID 31474989, 2019). "Next, we sought to determine if MDSCs express the IL-8 receptors CXCR1 and CXCR2, and if MDSCs are attracted to the tumor by IL-8." (PMID 31781510, 2019). "(c) Expression of CCR2, CCR4, CCR5, CCR7, CXCR1, CXCR2 and CXCR7 on tumor-infiltrating mast cells by gating on CD45+CD117+FcεRI+ cells." (PMID 30808413, 2019). "Granulocytic MDSCs, mainly composed by different subsets of neutrophils, express CXCR1 and CXCR2, and are recruited to the tumor by CXCL8, produced by tumor cells or by Treg." (PMID 30319638, 2018). "These cells express CXCR1 and CXCR2 at their surface and are recruited by their ligands including CXCL1 and CXCL2 which can be produced by tumor, endothelial cells or fibroblasts." (PMID 29983866, 2018). "Inhibition of CXCL8–CXCR1/2 signaling by CXCL8 antibodies, or small molecules targeting CXCR1 and/or CXCR2, also decreases tumor growth and progression in tumor mouse models." (PMID 30304046, 2018). "Neutrophils expressing CXCR1 and CXCR2 are attracted to the tumor site following a gradient of concentration of CXCL8 secreted by tumor cells." (PMID 29977225, 2018). "In the tumor nests of human ESCC tissues, various levels of CXCR1 or CXCR2 were observed: low and high compared to the normal squamous epithelia as a positive control." (PMID 29285315, 2017). "More importantly, we show that CXCR1/2‐mediated pneumotropism can be annihilated, since navarixin significantly prevented lung tumor colonies sprouted by circulating NRAS‐mutant tumor cells." (PMID 28341702, 2017). "CXCR1 and CXCR2 chemokine receptors and their ligands (CXCL1/2/3/7/8) play an important role in tumor progression." (PMID 28129639, 2017). "Significantly, inhibition of the IL-8 signaling pathway by reparixin, an inhibitor of the IL-8 receptor, CXCR1/2, reduced MDA-MB-231 tumor growth and metastasis." (PMID 28947965, 2017). "Previous studies demonstrated that different CXCR1 and CXCR2 antagonists can block these receptors inhibiting inflammation and tumor growth in various animal models." (PMID 28129639, 2017). "This cytokine is able to initiate multiple signaling pathways by activating two cell surface G-protein coupled receptors, CXCR1 and CXCR2, resulting in angiogenesis, tumor metastasis and tumorigenesis." (PMID 28881741, 2017).